STAT3 (signal transducer and activator of transcription 3)
Diseases named in the same sentence as STAT3 in open-access papers (continued):
Sharing a sentence is not in itself a finding about the gene and the disease.
pancreatic adenocarcinoma (26 papers, 2016 to 2025). "This study represents one of the first translational investigations of IL-6/GP130/JAK/STAT3 signaling in pancreatic adenocarcinoma." (PMID 41397158, 2025). "STAT3 has also been reported to be activated by Src in human pancreatic adenocarcinoma cells (independently from JAK activation)." (PMID 40699751, 2025). "This study investigates the activation of the IL-6/GP130/JAK/STAT3 pathway in archived biopsy samples from patients with pancreatic adenocarcinoma, quantifying its expression in both tumor and stromal compartments." (PMID 41397158, 2025). "The use of signal transducer and activator of transcription 3 (STAT3) antisense oligonucleotides in murine orthotopic pancreatic adenocarcinoma models further validated the therapeutic potential of targeting Tregs." (PMID 36797782, 2023). "RLX has shown efficacy against pancreatic adenocarcinoma growth through ERβ and the IL-6/gp130/STAT3 signaling pathway interference in PDAC cell line." (PMID 35708464, 2022). "The purpose of this study was to provide a comprehensive summary of therapeutic approaches targeting the GP130/JAK/STAT3 pathway in pancreatic adenocarcinoma through a systematic qualitative review of the literature." (PMID 34138876, 2021). "This study aims to evaluate the activation of the IL-6/GP130/JAK/STAT3 signaling pathway in previously collected tissue samples—including pancreatic biopsies, surgical specimens, and liver biopsies—from patients diagnosed with pancreatic adenocarcinoma." (PMID 41397158, 2025). "Targeting the IL-6/glycoprotein 130 (GP130)/JAK/STAT3 axis may therefore represent a promising therapeutic approach for pancreatic adenocarcinoma." (PMID 41397158, 2025). "As expected, human PanNETs and MAP model tumors exhibit distinct transcriptional programs from those found in the KRAS-driven pancreatic adenocarcinoma KPC model, including those associated with inflammatory response, allograft rejection, NFkB, STAT3, and KRAS pathways." (PMID 38609433, 2024). "STAT3 targeting has been proposed as a therapeutic option in pancreatic adenocarcinoma." (PMID 30065235, 2018). "Considering the substantially important roles of STAT3 in the development and progression of a large number of cancer types, we speculated that blocking IL-6 expression in STAT3 signaling may be valuable in the treatment of pancreatic adenocarcinoma." (PMID 29693005, 2018). "DCA activates EGFR, MAPK, and STAT3 signaling through TGR5 receptor and induces tumorigenicity in pancreatic adenocarcinoma cells." (PMID 37145211, 2023). "In pancreatic adenocarcinoma, the synergism was ascribed to several interacting mechanisms, encompassing inhibition of AKT signaling, increased STAT3 phosphorylation, and prominent induction of the CDK inhibitor p57KIP2." (PMID 29312470, 2018). "For example, in pancreatic adenocarcinoma, both PI3K and Stat3 activation downstream of ErbB1 were found to be essential for Ras-induced transformation." (PMID 27447549, 2016). "Anti-apoptotic proteins like BCL-2 may be induced by activated STAT3, and in pancreatic adenocarcinoma cells, the combination of JQ1 and SAHA diminished STAT3 phosphorylation to downregulate BCL-2." (PMID 29312470, 2018).
type 1 diabetes (26 papers, 2013 to 2026). "A recent review summarized the roles of STAT (STAT1, STAT3 and STAT5b) monogenic mutations in type 1 diabetes." (PMID 35242127, 2022). "Mutations in STAT3 are also implicated in the development of autoimmune diseases, including type 1 diabetes." (PMID 35270020, 2022). "STAT3 is involved in many immune system processes, and heterozygous gain-of-function STAT3 mutations, inherited in a dominant manner, have been associated with early-onset multisystem autoimmune diseases, including type 1 diabetes." (PMID 40868191, 2025). "Mutations in the transcriptional regulator STAT3 lead to neonatal type 1 diabetes." (PMID 36059506, 2022). "STAT3 GOF was initially discovered through genetic sequencing of a cohort of patients with early-onset type I diabetes, and this was initially considered a major feature of the disease." (PMID 36843887, 2022). "The original clinical descriptions of patients with STAT3 GOF included early onset type I diabetes mellitus, post-natal growth failure, and lymphoproliferation." (PMID 36843887, 2022). "STAT3 has been shown to mediate effector T-cell resistance to suppression in patients with type 1 diabetes." (PMID 33785863, 2021). "The STAT3 was detected in the TLR2-positive glomeruli in the STZ-induced type 1 diabetic mice and in the diabetic mice administered Pg-LPS." (PMID 29018490, 2017). "Endogenous synthesis of IL-1β is diminished in nerve tissue in type 1 diabetes and we propose this defect triggers reduced STAT3 signaling and mitochondrial function leading to sup-optimal axonal regeneration and plasticity." (PMID 24152426, 2013). "CXCL16 plays roles in the inflammatory response, cell proliferation and migration, and angiogenesis by promoting STAT3 phosphorylation and activating the STAT3/NF-κB pathway in islet-related inflammatory reactions (such as Type I diabetes) and tumour-related inflammatory reactions." (PMID 40165931, 2025). "Furthermore, 3 fold-lower levels of p-STAT3 expression can be detected in long-term STZ induced type 1 diabetic mice, likely contributing to the poor regenerative capacity observed in diabetic neurons." (PMID 36362354, 2022). "Administration with STAT3 inhibitor, S3I-201, prevents DN in type 1 diabetic mice." (PMID 31699972, 2019). "Genetics have a crucial role in the susceptibility of diabetes type 1; the most common genes related to type 1 diabetes are CTLA-4, PTPN22, STAT4, STAT3, and IFIH1." (PMID 34342790, 2021).
adenoma (25 papers, 2010 to 2026). A neoplasm arising from the epithelium. "Indeed, GSEA showed that loss of Mir34a in adenomas, and to a lesser extent in tumoroids, was associated with the induction of STAT3, JUN and SRF expression signatures." (PMID 36147476, 2022). "These adenomas were characterized by glandular structures, goblet-like cells, and extensive staining for activated signal transducer and activator of transcription 3 (STAT3)." (PMID 40673273, 2025). "As a transcriptional factor in these adenomas, STAT3 regulates several genes that control hormone regulation and cell proliferation." (PMID 39139281, 2024). "Act1 downregulation in macrophages activates STAT3 that promotes adenoma-adenocarcinoma transition via CXCL9/10-CXCR3-axis in CRC cells and PD-1/PD-L1-axis in CD8+ T cells." (PMID 36978108, 2023). "Our results showed that Act1 downregulation in macrophages activates STAT3 to promote adenoma-adenocarcinoma transition via CXCL9/10-CXCR3-axis in CRC cells and immunosuppression via PD-1/PD-L1-axis in CD8+ T cells." (PMID 36978108, 2023). "Taken together, our findings confirmed that Act1 downregulation in macrophages activates STAT3 to promote adenoma-adenocarcinoma transition via CXCL9/10-CXCR3-axis in CRC cells and immunosuppression via PD-l/PD-L1 axis in CD8+ T cells." (PMID 36978108, 2023). "In the context of the AOM-DSS model, deletion of STAT3 in colonic epithelium reduces the number and size of adenomas, yet the AOM-DSS–challenged colon still shows multifocal flat low-grade intraepithelial neoplasia." (PMID 35260534, 2022). "Collectively, these results argue strongly that miR-21 is a transcriptional target for Stat3 in gastric epithelium and the corresponding adenomas." (PMID 35053428, 2022). "Given the significance of PTEN as a hallmark tumor suppressor in a majority of human malignancies, including GC, we next assessed the functional contribution of Pten to Stat3-driven adenoma formation in the Gp130F/F model." (PMID 35053428, 2022). "Taken together, our results indicate that BMX and HCK promote colorectal epithelial cell proliferation and adenoma formation through the STAT3 signaling pathway." (PMID 35221332, 2022). "In adenomas deletion of Mir34a enhanced proliferation, STAT3 signaling, infiltration with fibroblasts, immune cells and microbes, and tumor stem cell abundance and decreased apoptosis." (PMID 36147476, 2022). "In order to demonstrate that the increased expression of miR-21 was dependent of Stat3 signaling, we assessed the miR-21 expression in the stomachs of Gp130F/F;Stat3+/− mice, in which Stat3 expression is globally restrained and adenoma formation is blocked." (PMID 35053428, 2022). "In human CRCs, the Mir34aΔIEC adenoma gene signature was associated with EMT, inflammation and actin cytoskeleton signatures, as well as with the TNFα/NFKB, IL6/STAT3 and MAPK signaling pathways." (PMID 36147476, 2022). "In contrast, deregulation of STAT3 is thought to occur in late stage adenomas or invasive carcinomas." (PMID 25348333, 2014). "Together, these data suggest that STAT3 suppresses malignant transformation of adenomas in the Apcmin/+ mouse strain." (PMID 24995503, 2014). "Levels of activated STAT3 (pY-STAT3) were increased 3.3-fold in the epithelium and stroma of dysplastic mucosa (147 ± 46; mean ± SD; and n = 4) vs. normal mucosa (45 ± 26; n = 7; and p ≤ 0.05, Kruskal–Wallis test) and were correlated with the adenoma number." (PMID 41226842, 2025). "Indeed, our results expand on previous observations that excessive STAT3 activity in the gastric epithelium mediated by IL-11 triggers the formation of non-invasive adenomas in gp130F/F mice." (PMID 39128004, 2024). "However, early adenoma stages are already fueled by aberrant STAT3 activity as a result of an oversupply of inflammatory cytokines, which is often observed even in the absence of overt gastritis." (PMID 39128004, 2024).
adenoma (continued). "Furthermore, loss of Mir34a in adenomas was associated with the induction of RNAs commonly up-regulated after IL6 treatment, which includes STAT3 activation." (PMID 36147476, 2022). "Consistent with the finding that activation of CSF1R induces STAT3 phosphorylation (p-STAT3) in CRC cell lines 21, the frequency of cells displaying STAT3 activation was decreased in adenomas of Csf1rΔIEC;ApcMin/+ mice, whereas deletion of Mir34a increased the number of p-STAT3-positive tumor cells." (PMID 36147476, 2022). "Wnt and STAT3 signalling are activated at opposite ends of the adenoma–carcinoma sequence." (PMID 25348333, 2014). "STAT3 activation by PG might required high level of progastrin expression, as found in adenomas or adenocarcinomas." (PMID 24209454, 2013). "STAT3 mRNA levels were higher in cortisol-secreting ACT (P = 0.01) and in adult adenomas (P < 0.01)." (PMID 42189769, 2026). "During the adenoma stage, SOCS3 is downregulated and inactivated, leading to sustained activation of STAT3; in advanced stages, it is further silenced through mechanisms such as CpG island methylation." (PMID 41376630, 2025). "The results above suggested that levels of activated (pY)-STAT3 were increased in dysplasia vs. normal colonic mucosa and that TTI-101 decreased adenomas by reducing the levels of pY-STAT3 in dysplastic mucosa." (PMID 41226842, 2025). "This study showed that it acts as an oncogenic miRNA in gonadotroph and corticotroph adenoma cells where it activates MAPK, PTEN/AKT and STAT3 signaling pathway." (PMID 38201476, 2023). "Considering the non-genomic factors contributing to adenoma pathogenesis, the signal transducer and activator of transcription 3 (STAT3) is an overexpressed gene in somatotroph adenomas." (PMID 37373068, 2023). "Conversely, it has also been suggested that STAT3 does not affect tumorigenesis, but the downregulation of Snail1 inhibits the transition from adenoma to cancer in Apc (Min/+) mice." (PMID 36010693, 2022). "Apc (Min/+) mice lacking STAT3 had a reduced occurrence of and suppressed the growth of early adenomas." (PMID 36010693, 2022). "Conversely, both non-tumor BRAFV600E parenchyma and adenomas showed increased pSTAT3 staining compared to controls, thus indicating that BRAFV600E activates STAT3, but not SMAD3, in the lung and potentially suggesting that p21CIP1 may be induced via STAT3 in BRAFV600E lung parenchyma." (PMID 35145078, 2022).
fibrosarcoma (24 papers, 2009 to 2025). A malignant mesenchymal fibroblastic neoplasm affecting the soft tissue and bone. "Recent studies also found that treatment with 2-DG abrogated STAT3 activation in leukemic cells and fibrosarcoma cells, but the underlying mechanisms were unclear." (PMID 29552018, 2018). "Mitochondrial STAT3 has been linked directly to increased ROS generation in at least two distinct signaling contexts: TNF-α-mediated necroptosis in L929 mouse fibrosarcoma cells and NGF-dependent neurite outgrowth in PC12 cells." (PMID 24671708, 2014). "For example, in fibrosarcoma and CHO cells, diminished STAT3 activity was associated with reduced ATR induction." (PMID 37126127, 2023). "Of interest, it has been recently demonstrated that STAT-3 inhibition induces apoptosis of different types of fibrosarcoma cells." (PMID 35740967, 2022). "A recent study showed that deletion of STAT3 stimulates one of the hallmarks of ICD in fibrosarcoma cells." (PMID 31192135, 2019). "The role of STAT3 in DNA damage has been highlighted in fibrosarcoma, where cells with low STAT3 levels have decreased ATM-Chk1 and ATM-Chk2 via transcriptional regulation of MDC1." (PMID 29262529, 2017). "Indeed, we demonstrated that the levels of STAT3 and pSTAT3 were increased in human fibrosarcoma cells with ectopic FUS-DDIT3 expression." (PMID 35186752, 2022). "Interestingly, in the HT-1080 human fibrosarcoma cell line, it has been reported that PIBF is implicated in the augment of STAT3 phosphorylation." (PMID 28168193, 2017). "Therefore, authors show that HBV can activate various pathways, such as Phosphatidylinositol 3-kinase-AKT serine/threonine kinase (P13K–AKT), Janus Kinase-Signal transducer and activator of transcription 3 (Jak-STAT3), or Rat sarcoma virus gene-Rapidly accelerated fibrosarcoma (RAS–RAF)." (PMID 39149606, 2024). "Finally, with recent evidence demonstrating that Pyr and MTX induce their anti-cancer activity (at least in part) by halting STAT3 transcriptional activity, these compounds were assessed in the STAT3-dependent luciferase reporter assay using U3A (male) fibrosarcoma cells, as performed previously." (PMID 36837770, 2023). "It has been shown that the pharmacological effects of G-CSF on BM stem cell populations are directly promoted via activation of signal transducer and activator of transcription 3 (STAT3) and rat sarcoma (RAS)/rapidly accelerated fibrosarcoma (RAF) signaling." (PMID 35676930, 2022). "We further verified this observation by treating matrix embedded fibrosarcoma cells with inhibitors of JAK2 and STAT3." (PMID 30220965, 2018). "To determine if the MLS-specific fusion oncoprotein FUS-DDIT3 regulates the JAK-STAT pathway, we compared the protein expression of STAT3 in the fibrosarcoma cell line HT1080 with and without ectopic FUS-DDIT3 expression." (PMID 35186752, 2022). "Another group has reported that PAI-1 promotes M2 polarization of monocytes via an IL6/STAT3 autocrine loop in fibrosarcoma; however, we did not observe M2 polarization following rhPAI-1 treatment." (PMID 33311557, 2021). "Although a link was found between CXCR4 and STAT3 in different cells, such as haematopoietic progenitor cells or a fibrosarcoma cell line, there are no reports on STAT3 signalling in SCLC so far." (PMID 19455144, 2009). "It should be pointed out that our data are somewhat not consistent to a recent study showing that deletion of STAT3 stimulates one of the hallmarks of ICD, namely the production of type 1 interferons, but not other ICD markers in fibrosarcoma cells." (PMID 31192135, 2019). "However, SU11248 caused a significant reduction in constitutive levels of AKT and Stat3 phosphorylation of in all the fibrosarcoma cells; after overnight incubation with SU11248, the phosphorylation levels of both AKT and Stat3 returned back to their original basal levels (data not shown)." (PMID 25119572, 2014).
intrahepatic cholangiocarcinoma (24 papers, 2017 to 2025). A carcinoma that arises from the intrahepatic bile duct epithelium in any site of the intrahepatic biliary tree. "For instance, the biogenesis of circRNA GGNBP2 (cGGNBP2) was mediated by IL-6/STAT3 pathway activation, and IL-6/cGGNBP2-184aa (a protein encoded by cGGNBP2)/STAT3 formed a positive feedback loop to promote tumor progression for intrahepatic cholangiocarcinoma." (PMID 37264406, 2023). "Specifically, the STAT3+ group in our cohort contained a lower proportion of intrahepatic cholangiocarcinoma (iCCA), which generally have a poorer prognosis compared to extrahepatic subtypes." (PMID 40426911, 2025). "lncRNA TUG1 sponging of miR-145 promoted intrahepatic cholangiocarcinoma progression, and regulated glutamine metabolism through the signal transducer and activator of transcription 3 (STAT3)/GDH axis." (PMID 34039257, 2021). "In terms of mechanism, OSM (oncostatin M), which is preferentially expressed by TANs, and IL-11, which is preferentially expressed by TAMs, jointly activate STAT3 signaling in ICC (intrahepatic cholangiocarcinoma) cells, thus achieving the tumor promoting effect." (PMID 38279145, 2024). "These factors activate STAT3 signaling and promote intrahepatic cholangiocarcinoma (ICC) cell proliferation, invasion, and colony formation." (PMID 40034694, 2025). "In the context of intrahepatic cholangiocarcinoma (ICC), tumor-associated neutrophils (TANs) exhibited a pro-tumorigenic character by producing elevated levels of oncostatin M, activating STAT3 signaling in ICC cells." (PMID 38474175, 2024). "In intrahepatic cholangiocarcinoma (ICC), IL-6 increases the expression of circRNA GGNBP2 to encode the protein cGGNBP2-184aa, which in turn forms a positive feedback loop of IL-6/cGGNBP2-184aa/STAT3 to facilitate ICC progression." (PMID 38890694, 2024). "Moreover, the inhibition of CCL18-mediated STAT3 phosphorylation, through immune responsive gene 1 (IRG1) overexpression, can inhibit macrophages M2-like polarization and impair the progression of intrahepatic cholangiocarcinoma (ICC)." (PMID 38542388, 2024). "On the other hand, overexpression of inflammatory genes, cytokines or STAT3, could result in the development of CCA, especially intrahepatic cholangiocarcinoma (ICC)." (PMID 33750398, 2021). "Previous study has identified it as a prognostic biomarker of perihilar and distal cholangiocarcinoma but not intrahepatic cholangiocarcinoma, the gene promotes extrahepatic cholangiocarcinoma metastasis by facilitating the epithelial-mesenchymal transition via the PLA2G4A/PGE2/STAT3 pathway." (PMID 32514252, 2020).